HOXB9 (homeobox B9)
Diseases named in the same sentence as HOXB9 in open-access papers (continued):
Sharing a sentence is not in itself a finding about the gene and the disease.
tumor (continued). "For the investigation of tumor suppression by bevacizumab administration, we performed the multiplex assay for comprehensive detection of enhanced cytokine production induced by HOXB9 in co-culture experiments." (PMID 24885802, 2014). "Homeobox B9 (HOXB9), a transcriptional factor, regulates developmental processes and tumor progression and has recently been recognized as one of important transcriptional factors related to angiogenesis." (PMID 24885802, 2014). "HOXB9 induced angiogenesis and tumor proliferation in vitro, which resulted in high tumorigenicity in vivo and poor overall survival." (PMID 24885802, 2014). "Several of these genes were differentially expressed between tumour and normal tissue, and two, HOXB9 and HOXD10, were highly expressed in pre-malignant and primary tumour tissue but not in metastases or normal cells." (PMID 25525461, 2014). "Knockout of either HOXB9 or ODC1 suppressed HFD-induced subcutaneous tumor growth." (PMID 41402312, 2025). "Many researchers are using various methods to reduce the expression of HOXB9 in tumor cells." (PMID 41515958, 2025). "Sherry Y's team confirmed that miR‐192, EGR1 and HOXB9 might be regulated by the same upstream factors and thus participate in tumour angiogenesis and invasion." (PMID 40936205, 2025). "Targeting ODC1 and HOXB9 inhibits tumor formation and LNM in xenograft models." (PMID 41402312, 2025). "Research has shown that HOXB9 might play important roles in regulating MT in tumour cells and the self‐renewal ability of stem cells, thus affecting the malignant phenotypes of tumour cells." (PMID 40936205, 2025). "Given its known roles in tumor progression and immune modulation 62, 63, HOXB9 upregulation may further contribute to the immune suppression observed in the IGF2BP-H group." (PMID 41049442, 2025). "The correlation between tumor-infiltrating immune cells and HOXB9 expression was also analyzed." (PMID 37657018, 2023). "Based on these findings, it is reasonable to propose that HOXB9 could be a promising target for tumor immunity and a valuable prognostic marker for different types of cancer." (PMID 37301547, 2023). "In addition, HOXB9 expression was positively correlated with tumor malignancy in the GEPIA and UALCAN databases (P < .05), and negatively with patient prognosis in both databases (P < .05)." (PMID 37657018, 2023). "In this study, we systematically analyzed and described the role of HOXB9 in multiple tumors and suggested that HOXB9 may become a valuable tumor biomarker to a great extent." (PMID 37301547, 2023). "Among the most overexpressed genes in tumor cells compared to normal tissue are genes coding for transcription factors (HOXB9, SIM2, ZIC5, SP8, TFAP2A, FOXE1, HOXB13, and SALL4), cancer testis antigens (CT83), and cytokines activating regulatory Th17 cells (IL23A)." (PMID 37228492, 2023). "Furthermore, HOXB9 expression was strongly correlated with the tumor stage, and was significantly higher in the middle and advanced stages compared to the earlier stages, which suggests a potential function of HOXB9 in tumor development and metastasis." (PMID 37657018, 2023). "Based on the consistent results obtained by univariate and multivariate Cox regression analysis, it is reasonable to think the high expression of HOXB9, high stage, high grade, tumor invasion greater than 50%, and histological type, and age greater than 60 years jointly affect the OS in EC patients." (PMID 36803556, 2023). "It is worth noting that HOXB9 was significantly associated with the pathological stages of several tumors, including CESC, HNSC, PAAD, and LIHC, which also showed HOXB9 expression had a forceful association with the degree of tumor infiltrations." (PMID 37301547, 2023). "Similarly, miR-215 acts as a tumor suppressor by blocking the EGFR ligand epiregulin, and its transcriptional regulator HOXB9, which was upregulated in hUCMSC-derived exosomes, confirming their tumor suppressor activity." (PMID 35511336, 2022).
tumor (continued). "We then confirmed the function of HOXB9 in tumor growth, in vivo." (PMID 36158877, 2022). "In our gain-of-function experiments, we found that HOXB9 overexpression significantly increased in vitro cell proliferation, indicating a tumour-promoting role; however, the mechanism by which HOXB9 affects cell proliferation in CRC is still unknown." (PMID 35216396, 2022). "Given that the brain microvascular ECs were the first kind of cells that interacted with the metastatic tumor cells extravasating from the vessels, we performed a co-culture experiment to determine the expression modulation of HOXB9 in lung tumor cells educated by HBMECs." (PMID 34055607, 2021). "Recent studies showed that HOXB9 was a critical transcription factor for the drug resistance of tumors, the expression silence of which would be very promising for ameliorating the resistance of tumor cells to the agent." (PMID 34055607, 2021). "Together these data suggest that elevated HOXB9 expression in ACC may play a role in tumour progression to aggressive disease." (PMID 33214683, 2021). "To investigate if HOXB9 can promote tumour formation we bred Sf-1:Hoxb9 mice with mice containing the activating conditional Ctnnb1 deletion allele and a construct with Cre recombinase driven by Cyp11a1-regulatory sequences (Ctnnb1 mutant mice, referred to as ABC)." (PMID 33214683, 2021). "Post-hoc meta-analysis for HOXB9 protein found no statistical association between high HOXB9 and tumour depth (OR 0.92, 95% CI: 0.21–3.97, p = 0.910)." (PMID 34948228, 2021). "In addition, the pairing analysis in which the normal and tumor samples were derived from the same patient further confirmed the differential expression of HOXB9 in the normal and tumor tissue." (PMID 34055607, 2021). "We speculated that HOXB9 might block the Wnt signaling pathway and inhibit tumor growth through MYC and CTNNB1." (PMID 34306077, 2021). "Consequently, the roles of HOXB9 in tumorigenesis and disease progression seem to vary between different tumor types, and this indicated the complex roles and mechanisms underlying tumorigenesis and disease progression." (PMID 34055607, 2021). "Collectively, these findings suggested that the brain metastatic tumor cells may have upregulated the expression level of HOXB9, which strengthened the intracranial tumorigenicity." (PMID 34055607, 2021). "In addition to its crucial roles in development, HOXB9 plays an important role in numerous human solid cancers and its aberrant expression significantly contributes to tumor formation." (PMID 33171691, 2020). "In contrast, HOXB9 might play a tumor suppressor function in gastric adenocarcinoma cells, as its overexpression increases apoptosis and inhibits metastasis formation." (PMID 33411683, 2020). "In addition, IHC analysis showed higher HOXB9 expression in patient-derived NSCLC brain metastases compared to matched primary tumor specimens." (PMID 33411683, 2020). "HOXB9 is upregulated in many type of cancers and has been proposed as a factor modulating the expression of alternative proinflammatory and pro-angiogenic secreted factors in the tumor microenvironment." (PMID 33171691, 2020). "To evaluate the impact of HOXB9 expression in tumor cells on junctional proteins involved in endothelial barrier function, we examined the expression of ZO-1, claudin-5, and VE-cadherin in HUVECs after co-culture with tumor cells." (PMID 33411683, 2020). "Indeed, HOXB9 modulates the expression of alternative pro-angiogenic secreted factors in the tumour microenvironment leading tumor escape from the anti-angiogenic treatments." (PMID 33171691, 2020). "However, both oncogenic and tumor suppressor functions have been attributed to HOXB9 in different cancers." (PMID 33411683, 2020). "HOXB9 is another potent driver of angiogenesis, promoting angiogenic recruitment by tumor cells." (PMID 31013831, 2019).
tumor (continued). "HOXB9 is known as a highly conserved homeobox transcription factor gene which drives neoplastic transformation and tumor progression exerting an anti-apoptotic effect and promoting tumor cell invasion." (PMID 34532592, 2018). "We next assessed whether the anti-angiogenic effect of miR-192 can be abrogated by EGR1 and/or HOXB9 expression in SKOV3ip1 tumours." (PMID 27041221, 2016). "Importantly, significant reductions in EGR1 and HOXB9 levels were observed in tumours following two doses of miR-192-DOPC treatments, compared with tumours treated with control miRNA-DOPC." (PMID 27041221, 2016). "The central role of EGR1 and HOXB9 in tumour angiogenesis has recently been recognized." (PMID 27041221, 2016). "Three possible sites of HOXB9 tumor suppression in GC cells were identified." (PMID 26536658, 2015). "Therefore, this study identified the hexapeptide motif as a “brake” in HOXB9 that limits its tumor suppressive activity in GC cells." (PMID 26536658, 2015). "The results of these regulatory effects could lead to either oncogenic or tumor suppressive roles of HOXB9, depending on the context of the particular type of cancer involved." (PMID 26536658, 2015). "Therefore, further understanding of the roles of HOXB9 in GC and identifying its molecular regulatory sites and detailed mechanisms of tumor suppression will facilitate in the development of novel clinical therapeutic regimens." (PMID 26536658, 2015). "Then, we hypothesized that anti-angiogenic treatment may cause strong regression in tumors with such angiogenic properties as HOXB9, which depends tumor proliferation on enhanced angiogenesis and stromal reaction in the microenvironment." (PMID 24885802, 2014). "On the basis of these background information, we hypothesized that to target this coordinated program orchestrated by HOXB9 may be required for effective inhibition of tumor progression, and focused on the mechanisms of HOXB9 transcription." (PMID 25136922, 2014). "Additionally, in the tumor tissues of EC patients with LVSI or LNM from 2014–2020, a significant correlation between HOXB9 and ODC1 (r = 0.56, p = 0.02) is demonstrated by IHC, indicating the association between HOXB9 and ODC1 at the protein level." (PMID 41402312, 2025). "While the expression of HOXB9 in primary tumors was shown to be upregulated, it may be conjectured that during the tumorigenesis and progression of the disease, HOXB9 played a pro-tumor role and that this tumor-favored effect was further potentiated by the brain metastatic microenvironment." (PMID 34055607, 2021). "Therefore, targeting the expression of HOXB9 could be a promising approach to modulate the tumor resistance to anti-angiogenic treatments." (PMID 33171691, 2020). "HOXB9 could be a crucial transcription factor in sustaining tumor resistance to anti-VEGF treatment via modulation of the expression of alternative proinflammatory and pro-angiogenic secreted factors and via the recruitment of a subset of inflammatory immunosuppressive cells." (PMID 33171691, 2020). "Thus, these on-and-off results for HOXB9 expression and neutralizing antibodies suggest our hypothesis that bevacizumab inhibits HOXB9 induced tumor proliferation by silencing microenvironmental cytokine release including VEGF and IL6." (PMID 24885802, 2014). "Therefore, the role of the microenvironment in tumor proliferation under the regulation of HOXB9 was investigated, given that the primary difference between the in vivo and in vitro conditions was the existence of a microenvironment including vessels and fibroblasts." (PMID 24885802, 2014). "Bevacizumab, an anti-vascular endothelial growth factor (VEGF) antibody, remarkably suppressed tumor proliferation by inhibiting angiogenesis in HOXB9-overexpressing xenografts, and it improved overall survival and provided prolonged progression-free survival in HOXB9-overexpressing patients." (PMID 24885802, 2014).
tumor (continued). "Lipid droplet staining indicated more lipid droplets in the tumor tissues of the HFD group, while knocking down HOXB9 or ODC1 reduced lipid droplet formation." (PMID 41402312, 2025). "This long-term positive feedback in a continuous daily cycle has a more profound impact on HOXB9, ODC1, polyamine accumulation, and tumor progression than mere upregulation." (PMID 41402312, 2025). "In the subcutaneous xenograft tumor model, HFD promoted in situ tumor growth, whereas knockdown of ODC1 or HOXB9 attenuated this effect." (PMID 41402312, 2025). "Ishikawa cells stably transfected with sgRNAs targeting HOXB9 exon 1 and ODC1 exon 4 were used to establish a subcutaneous xenograft tumor model." (PMID 41402312, 2025). "In our study, through the difference analysis of mRNA data of the HNSCC tumor and normal group in the TCGA database, it was found that HOXB7 and HOXB9, located on the same chromosome of HOXB-AS4, were significantly different." (PMID 40657360, 2025). "Immunohistochemical staining of the tumor tissue demonstrated strong expression of ERCC-1, MRP-2, and XIAP in most of the HOXB9 OE/SKOV3-injected group tumors compared with the control SKOV3-injected group tumors." (PMID 36674764, 2023). "IF imaging revealed that the HOXB9 protein was localized in the nucleus in HEK293, Hela, and U-2 OS tumor cell lines." (PMID 37301547, 2023). "The University of Alabama at Birmingham (UALCAN) database was used to analyze the relative expression of HOXB9 in HNSCC subgroups based on clinicopathological features, including cancer stage, tumor grade and lymph node stage." (PMID 37657018, 2023). "The transcript levels of HOXB1, HOXA7, HOXB5, HOXD8, HOXB9, HOXA9, and HOXA11 were significantly lower in ccRCC tumor tissues compared to adjacent normal tissues, which was consistent in both TCGA and ICGC cohorts." (PMID 36387262, 2022). "Consistent with our previous study, HOXB9 promoted HCC cell proliferation and migration in vitro, as well as tumor growth in vivo." (PMID 36158877, 2022). "For example, in lung cancer, HOXB9, as a classical Wnt/TCF signaling pathway target, can significantly improve the invasion and metastatic potential of tumor cells and directly mediate the brain metastasis of lung adenocarcinoma." (PMID 34306077, 2021). "The results revealed that the mRNA expression levels of DLX4, FBN1, HIC1, HOXB9, ONECUT2, and SIX1 were significantly different between tumor samples and normal tissues, which were consistent with the results from TCGA." (PMID 35095892, 2021). "To investigate the promotive role of HOXB9 in PCa metastasis, we isolated homogenous PCa subpopulations carrying different combinations of CSC markers from orthotopic PCa tumours." (PMID 34247196, 2021). "Taken together, this study provide a better understanding of the oncogenic mechanism of HOXB9, which can induce EMT of tumor cells and destroy the integrity of the BBB." (PMID 33411683, 2020). "Here we show that homeobox B9 (HOXB9), which is commonly overexpressed in NSCLC, promotes epithelial-to-mesenchymal transition (EMT) and tumor migration and invasion." (PMID 33411683, 2020). "HOXB9 also promotes the growth of colon cancer by activating IL6 signaling, inducing the secretion of angiogenic factors and increasing proliferation of tumor cells." (PMID 32104178, 2020). "HOXB9 is a transcription factor of the HOX family and plays an important role in embryo development and tumor progression." (PMID 33041670, 2020). "We found that HOXB9 can enhance the EMT process of NSCLC, which makes it easier for tumor cells to spread into the blood circulation, and eventually colonize the tumor to distant organs." (PMID 33411683, 2020). "Nanoliposome-mediated delivery of microRNA-192 is indicated as an effective therapeutic for suppressing tumor angiogenesis mechanistically through downregulation of EGR1 and HOXB9 expression in tumors." (PMID 31013831, 2019).
tumor (continued). "HOXB9 mRNA was also readily detected in GBM samples, albeit exhibiting some degree of inter‐ and intra‐tumour heterogeneity (Fig EV5B–D)." (PMID 31468686, 2019). "In the present study, HOXB9, another HOX gene, was overexpressed in LSCC and correlated with high tumor grade." (PMID 28808656, 2017). "It was shown that the expression of EREG and HOXB9 is significantly increased in tumor tissues compared with healthy tissues (P < 0.01 for EREG, P < 0.001 for HOXB9)." (PMID 29199273, 2017). "In contrast to the SKOV3ip1-EV tumours where miR-192 treatment resulted in a 90% reduction in tumour burden, only 65 and 30% reduction in tumour burden was observed for tumours expressing EGR1 and HOXB9, respectively." (PMID 27041221, 2016). "HOXB9, a putative downstream target of Wnt/TCF signaling that was dependent on GalNAc-T14 expression, contributed to metastatic tumor formation." (PMID 26544896, 2015). "HOXB9 promotes the secretion of angiogenic factors, including VEGF, to induce tumor proliferation through microenvironmental production of cytokines including IL6 signaling." (PMID 24885802, 2014). "Our previous work also revealed a non-transcriptional function of HOXB9: a glucose metabolism receptor that mediates tumor glucose reprogramming." (PMID 41402312, 2025). "Targeting HOXB9 or ODC1 reduces polyamine levels and suppresses tumor growth/spread." (PMID 41402312, 2025). "Therefore, knocking down HOXB9 or ODC1, or adding DFMO to drinking water effectively inhibits LNM as well as in-situ tumor growth, indicating a promising target for reversing of metabolic disorder promoted EC progress." (PMID 41402312, 2025). "The association analysis between the degree of HOXB9 expression and clinicopathological characteristics revealed a significant correlation between HOXB9 expression and HCC tumor volume, suggesting that HOXB9 may facilitate the growth of HCC." (PMID 36158877, 2022). "Taken together, our study suggested that aberrantly high HOXB9 expression in HCC could promote the proliferation, invasion, and migration ability of HCC tumor cells by activating TGF-β1-mediated Smads and ERK1/2 signaling pathways." (PMID 36158877, 2022). "Expression of VEGF-D mRNA, but not VEGF-C or VEGFR-3, was increased in tumor cells in vitro overexpressing HOXB9 compared with the checkpoint cells." (PMID 35330327, 2022). "The HOXB9 gene belongs to the HOX family and has been identified as a critical TF involved in numerous human solid tumours as its aberrant expression contributes to tumour growth, progression, and metastases." (PMID 35216396, 2022). "Second, in our study, we used the TMA approach to analyze HOXB9 protein expression in CRLM tissues, which potentially introduces selection bias as it consists of core biopsies instead of a larger section and limits the tumour-heterogeneity inspection." (PMID 35216396, 2022). "This staining pattern was unchanged in double-mutant tumours showing that elevated Hoxb9 had no major effect on this pathway." (PMID 33214683, 2021). "HOXB9 is in the HOX transcription factor family and was overexpressed in many types of tumours." (PMID 34247196, 2021). "Our data show that overexpression of Hoxb9 in the adrenal leads to an increase in foetal derived X-zone cells, but does not promote hyperplasia or neoplasia." (PMID 33214683, 2021). "The results showed that the expression of HOXB9 was positively observed in the bulk of metastatic loci and the depletion of HOXB9 in cells of LLC-BrM could attenuate the colonization and survivability of tumor cells in the brain." (PMID 34055607, 2021). "HOXB9, HOXD10 and HOXA5 were expressed at low levels in GC and acted as tumour suppressors." (PMID 32907552, 2020). "When we examined the mRNA expression levels of several tumor metastasis-related genes after knocking down HOXB9 (data not shown), we only found E2F3 mRNA expression levels were decreased significantly." (PMID 29724991, 2018).